CELF2 (CUGBP Elav-like family member 2)
Diseases named in the same sentence as CELF2 in open-access papers (continued):
Sharing a sentence is not in itself a finding about the gene and the disease.
tumor (40 papers, 2011 to 2025). "CELF2 encodes a tumor suppressor and is epigenetically silenced by DNA methylation in human cancers." (PMID 36230572, 2022). "CELF2 also had strong correlations with markers of diverse TIICs such as T cells, tumour‐associated macrophages and DCs in BRCA and LUSC." (PMID 34288370, 2021). "5’-aza-2’ deoxycytidine restores the IR caused by CELF2 and inhibits tumor cell growth." (PMID 37506056, 2023). "Indeed, we show that CELF2 deficiency in patient-derived GSCs drastically reduced tumor growth in the brains of nude mice." (PMID 37894405, 2023). "The restoration of CELF2 could inhibit tumor growth and the epigenetic loss induced an aberrant downstream pattern of alternative splicing." (PMID 34056873, 2021). "CELF2 (CUGBP Elav-like family member 2) is a tumor suppressor that encodes CELF2, a protein that is one of the six-member CELF family of proteins that are recognized for their wide-ranging function in regulating pre-mRNA splicing and controlling the translation and stability of mRNAs." (PMID 33282601, 2020). "CELF2 also functions in tumor initiation and progression given its consistently reduced expression during neoplastic transformation." (PMID 38701081, 2024). "We next assessed the effect of CELF2 knockdown on the tumor-initiating properties of GSCs in an orthotopic xenograft model in nude mice." (PMID 37894405, 2023). "We found that CELF2 is a major point of tumor vulnerability as its repression is sufficient to convert aggressive tumor cells into cells without the ability to form tumors in vivo." (PMID 37894405, 2023). "Taken together, these experiments provide compelling evidence that CELF2 is upregulated by HR and exerts a strong tumor-suppressive effect on BC cells." (PMID 36230572, 2022). "First, we performed the subcutaneous tumor formation experiment by injecting the cells that were transduced using the viruses and stably express the control vector or CELF2 into nude mice." (PMID 35941702, 2022). "In the IHC assay, CELF2 was found to be mainly expressed in the nucleus, and CELF2 expression in tumor tissues was also significantly lower than that in pericarcinomatous tissue." (PMID 35941702, 2022). "We further demonstrated that HR’s antitumor activity was at least partly mediated by transcriptional activation of CELF2, a tumor suppressor with RNA-binding activity." (PMID 36230572, 2022). "Following injection into the mammary fat pads in NOD SCID mice, tumor growth by CELF2-expressing MDA-MB-231 cells was markedly reduced compared with the control MDA-MB-231 cells." (PMID 36230572, 2022). "The protein and mRNA expression levels of CELF2 were significantly lower in PC tissues than in pericarcinomatous tissue, and low CELF2 expression is closely related to the occurrence of distant tumor metastasis." (PMID 35941702, 2022). "The tumor volume and weight of the nude mice in the CELF2 overexpression group were significantly lower than those in the control group after 5 weeks." (PMID 35941702, 2022). "We found that the protein and mRNA levels of CELF2 in tumor cells were lower than in normal pancreatic cells." (PMID 35941702, 2022). "IHC staining demonstrated that xenograft tumours derived from the ASO‐miR‐363‐3p transfected cells had significantly higher CELF2 expression than tumours in the control group." (PMID 34636136, 2021). "Overall, our study provides a reference and direction for understanding the crucial role of CELF2 in the immune microenvironment of pan‐cancer, as well as reveals the potential mechanism thereby CELF2 affects anti‐tumour immunity and cancer immunotherapy." (PMID 34288370, 2021). "The results revealed a significant correlation between CELF2 expression and the survival of patients with a variety of tumours, including blood, brain, breast, colorectal, eye, lung, ovarian, skin and soft tissue cancers." (PMID 34288370, 2021).
tumor (continued). "Comprehensive genomic analysis has shown that RNA‐binding proteins, including CELF2, are predominantly downregulated in tumours compared with their expression in normal tissues and play a crucial role in tumour development." (PMID 34636136, 2021). "In this study, we assessed the correlations of CELF2 expression with the abundance of TIICs in 39 tumour types from the TIMER database." (PMID 34288370, 2021). "According to numerous studies, CELF2, a tumor suppressor, is also downregulated by a number of miRNAs." (PMID 34681716, 2021). "In the meantime, TF TRIM65 upregulates CUGBP Elav-like family member 2 (CELF2) to promote tumor apoptosis and inhibit cell migration and proliferation." (PMID 32211020, 2020). "In conclusion, our data provide the evidence that CRNDE play important roles in HCC that is related to mediate epigenetic suppression of multiple tumor suppressive genes, especially CELF2 and LATS2." (PMID 32826865, 2020). "CELF2 shares similar structure with HuR, which is one of the well-known RBPs that play important roles in tumor development." (PMID 26314850, 2015). "In the present study, we explored the expression profile and mode of action of CELF2 in our collection of GBM tissue samples representative of mitotic tumor territories enriched in OLIG2-positive cells or, conversely, non-mitotic tumor areas poor in OLIG2-positive cells." (PMID 37894405, 2023). "The effect of CELF2 on tumor growth and distant metastasis was further explored in vivo." (PMID 35941702, 2022). "In addition, the expression level of Ki-67 in the tumor tissues of the CELF2 overexpression group was significantly lower than that of the control group, which further confirmed the anti-tumor effect of CELF2." (PMID 35941702, 2022). "In the MCCS, higher tumour methylation showed association with shorter overall survival for APC (HR = 1.28, 95% CI: 1.07–1.53), HIST3H2A/HIST3H2BB (HR = 1.28, 95% CI: 1.02–1.62), CELF2 (HR = 1.30, 95% CI: 1.07–1.58) and TMEM101 (HR = 1.21, 95% CI: 1.00–1.48)." (PMID 33461604, 2021). "Multiple studies have confirmed that CELF2 exerts tumour suppressive effects in most tumours, which is significantly increased in developing thymocytes and activated T cells, but its comprehensive understanding within the TME remains unknown." (PMID 34288370, 2021). "A significant correlation was shown between CELF2 expression and tumour purity in 28 tumours." (PMID 34288370, 2021). "Interestingly, the mRNA stability and trafficking of the COX-2 (Cyclooxygenase-2) tumor promoting agent to cytoplasmic SGs depends significantly on CELF2 RBP." (PMID 34681716, 2021). "Notably, the presence of T cells in cancer lesions correlates with a better patient prognosis in a variety of human malignancies, highlighting CELF2 as a potential tumor progression inhibitor." (PMID 34681716, 2021). "Furthermore, we demonstrated that CELF2 is strongly correlated with ICMs in various tumours, and significantly outperforms five prevalent biomarkers in predicting the responses to immunotherapy." (PMID 34288370, 2021). "Further evidence can be found in non-small-cell lung cancer, where CELF2 is capable of inhibiting tumor development by antagonizing PREX2 (Phosphatidylinositol-3,4,5-Trisphosphate Dependent Rac Exchange Factor 2)’s oncogenic impact and regulates PI3-K signaling." (PMID 34681716, 2021). "Meanwhile, we speculated that CELF2 may have an impact on tumor metastasis, and measured the invasion and migration efficiency in HCC cells." (PMID 32826865, 2020). "CELF2 exerted tumor suppressive effect in HCC and was involved in CRNDE-mediated oncogenic effect." (PMID 32826865, 2020). "CELF2 is a tumor suppressor with activity in cancers reported." (PMID 33282601, 2020). "CELF1 is a potent cancer driver whereas CELF2 is potential tumor suppressor." (PMID 31534127, 2019).
tumor (continued). "CELF2 is a tumor suppressor, and EFR3B contributes to the control of the phosphorylation state and could affect the responsiveness of G-protein-coupled receptors in higher eukaryotes." (PMID 31379917, 2019). "Therefore, CELF2 may be a crucial regulator of tumour immune cell infiltration and serve as a prognostic and immunotherapeutic biomarker in TNBC and LUSC." (PMID 34288370, 2021). "However, the comprehensive understanding of the impacts of CELF2 on the tumour immune microenvironment remains unknown." (PMID 34288370, 2021). "Combined with the indispensable role of DCs in anti‐tumour immunity and the promising future of DC vaccines in tumour treatment, we are confident that clarifying the mechanism by which CELF2 interacts with DCs in the TME may provide a new target for immunotherapy." (PMID 34288370, 2021). "Importantly, CELF2 was significantly associated with plenty of immune checkpoint molecules (ICMs) and outperformed five prevalent biomarkers including PD‐1, PD‐L1, CTLA‐4, CD8 and tumour mutation burden in predicting immunotherapeutic responses." (PMID 34288370, 2021). "However, the impacts of CELF2 on tumour‐infiltrating immune cells (TIICs) and clinical outcomes of tumours remain unclear." (PMID 34288370, 2021). "Further, EZH2 bound to TNK2-AS1 silenced the gene coding for CELF2 (CUGBP Elav-like family member 2) and exerted tumor-promoting effects through activation of the PI3K/Akt pathway." (PMID 38473229, 2024). "Through this mode of action, CELF2 can repress genes such as SOX3, which we have shown to oppose the phenotype of mitotic/OLIG2-positive tumor cells." (PMID 37894405, 2023). "CELF2 shapes a H3K9me3-repressive landscape in the SOX3 gene, thereby promoting a proliferating tumor cell phenotype." (PMID 37894405, 2023). "CELF2 was downregulated in PC tissues, which affected tumor TNM stage and tumor size, and low expression of CELF2 indicated a poor prognosis of PC." (PMID 35941702, 2022). "After overexpression of CELF2, the expression of CD44s was significantly decreased by AS of the CD44 pre-mRNA, and different key spliceosomes were formed, which inhibited tumor progression." (PMID 35941702, 2022). "Respectively, the expression of CDO1, CELF2, ITPRIPL1, KCNH8, RIC3, USP44 and ZSCAN23 was significantly lower in tumor tissues, whereas the expression of PTK6 and RAB25 was significantly higher in tumor tissues." (PMID 34056873, 2021). "In summary, elevated CELF2 expression is correlated with better prognosis and higher TIIC infiltration in a variety of tumours." (PMID 34288370, 2021). "In this study, we systematically summarized the expression levels and prognostic value of CELF2 in diverse cancer types using Oncomine and TIMER database, revealing prominent differences between tumours and adjacent normal tissues." (PMID 34288370, 2021). "Using qRT-PCR, we also verified that the gene AS events SORBS2 were downregulated in tumor tissue, and gene AS events EPB41L2, CELF2, TMEM130, and VCL were upregulated in tumor tissue." (PMID 34692669, 2021). "CUGBP Elav-like family member 2 (CELF2, also called CUGBP2) is a tumor suppressor that can inhibit cancer growth and induce apoptosis." (PMID 33066509, 2020). "Our investigations demonstrated for the first time that CELF2 was markedly downregulated in HCC patients and cell lines, and it functioned as a tumor suppressor gene in HCC." (PMID 32826865, 2020). "Similarly, TNK2-AS1 can bind to EZH2 and silence CUGBP Elav-like family member 2 (CELF2), with these processes subsequently activating the PI3K/Akt pathway in AML cells to promote tumor development." (PMID 39655332, 2024). "On the other hand, CELF2 expression is inversely correlated with that of miR-199a-3p, which is expressed in differentiated GBM cells and in OLIG2-negative, low-mitotic index tumor territories." (PMID 37894405, 2023).
tumor (continued). "In these cancers, CELF2 expression is down-regulated via promoter methylation or miRNA targeting, which is probably not the case in all aggressive tumor cells." (PMID 37894405, 2023). "Tumor growth, monitored using in vivo bioluminescence imaging, was detected in all mice grafted with GB5-shCTL or GB1-shCTL, whereas no signal was detected in mice grafted with cells depleted for CELF2 expression (shCELF2) even three to five weeks after transplantation." (PMID 37894405, 2023). "Patients #5, #6, and #7 (without tumor samples) showed an overlap of four genes (SORL1, PTPRC, MIR6819, and NAMPT), while #6 and #7 also shared five genes (CELF2, EDEM3, SMCHD1, RAVER1, and CXCR1)." (PMID 39001407, 2024). "Taken together, these results indicate that GBM cells not expressing CELF2 and GBM cells expressing it strongly coexist in the same tumor." (PMID 37894405, 2023). "Here, we show that the RNA binding protein CELF2 is strongly expressed in mitotic and OLIG2-positive GBM cells, while it is downregulated in differentiated and non-mitotic cells by miR-199a-3p, exemplifying GBM intra-tumor heterogeneity." (PMID 37894405, 2023).
cancer (31 papers, 2011 to 2025). A tumor composed of atypical neoplastic, often pleomorphic cells that invade other tissues. "We observed that bcf-eccDNA carrying LINC00598 or CELF2 had high diagnostic accuracy in cancer screening." (PMID 39920810, 2025). "By using an online database, we found that CELF2 was expressed at low levels in most cancers, whereas its mutation rate was low." (PMID 34636136, 2021). "The importance of cancer stem cell phenotype in determining the biological function of CELF2 is further underlined by the fact that CELF2 expression is repressed upon exit from stem cell status, promoted by serum or by miR-199a-3p expression, a pro-differentiating miRNA." (PMID 37894405, 2023). "We analysed CELF2 expression levels and mutation rates in various cancer types." (PMID 34636136, 2021). "Three clear examples are Cd44, Celf2, and Taok3 which are overall highly expressed in the process and related to cell adhesion or cancer progression." (PMID 36329018, 2022). "A pan-cancer analysis in 2021 demonstrated strong evidence of a correlation between CELF2 upregulation with better prognosis in multiple tumors, particularly in breast and lung cancers, where it was markedly associated with many immune checkpoint molecules." (PMID 34681716, 2021). "CELF2, a pleiotropic member that regulates many cancer-related genes, is primarily downregulated in tumors." (PMID 34681716, 2021). "We next investigated the impact of CELF2 expression on the prognosis of different cancers using PrognoScan." (PMID 34288370, 2021). "Another key finding of this study was that CELF2 expression correlated with diverse levels of immune infiltration in multiple cancer types, and especially in BRCA and LUSC." (PMID 34288370, 2021). "To further assess CELF2 expression in different cancer types, we used the TIMER tool to analyse RNA‐seq data from the TCGA database." (PMID 34288370, 2021). "The results showed that expression of CELF2 in cancer patients (n = 369) was slightly lower than in heathy humans (n = 160)." (PMID 32826865, 2020). "Next, we analyzed GEPIA-LIHC database, and compared the expression of CELF2 in healthy human bodies and in cancer patients." (PMID 32826865, 2020). "CELF2, also known as CUGBP2, is an RNA-binding protein and was reported to be implicated in several human cancers by acting as splicing regulator in nucleus." (PMID 32826865, 2020). "Previous studies have shown that miR-615 can increase the level of Mcl-1 protein and promote the proliferation and metastasis of cancer cells and the ability of antiapoptosis by inhibiting the expression of CELF2 in cancer cells." (PMID 31885571, 2019). "Opposite trends of expression changes were observed for QKI, MBNL1 and CELF2 in the KIRC compared to other cancer types (upregulation in KIRC versus downregulation in other cancer type)." (PMID 25908786, 2015). "CELF2 gene is located on chromosome 10p, a region frequently lost in human cancers." (PMID 38514854, 2024). "Herein, we delineated the expression and prognostic landscape of CELF2 across human cancers." (PMID 34288370, 2021). "We first analysed the expression levels of CELF2 mRNA in pan‐cancer using Oncomine database." (PMID 34288370, 2021). "In addition, CELF2 expression was also significantly associated with infiltration levels of B cells in 25 cancers, CD4+ T cells in 29 cancers, CD8+ T cells in 33 cancers, macrophages and DCs in 29 cancers and neutrophils in 32 cancers." (PMID 34288370, 2021). "CELF2 was expressed at different levels in cancer and normal tissues but was not extensively mutated in cancer." (PMID 34636136, 2021). "Overall, our study strongly confirmed that CELF2 could be used to evaluate prognosis and responses to immunotherapy in cancer patients and is superior to remaining prevalent biomarkers." (PMID 34288370, 2021).
cancer (continued). "Notably, despite the structural resemblance between CELF family members, particularly between CELF1 and CELF2 (>90% similarity in their RNA-binding domains), their functions are quite different, notably in cancer." (PMID 34681716, 2021). "Reduced expression was found in both HCC cancer patients and cell lines; therefore, we speculated that CELF2 may play important role in tumorigenesis and metastasis." (PMID 32826865, 2020). "Moreover, in hepatocellular carcinoma, it was noticed that the anti-cancer activity of brucein D is exerted by suppressing a CELF2-targeting miRNA, miR-95." (PMID 33066509, 2020). "COX-2 is upregulated in colorectal adenomas, thereby suggesting that CELF2 might prevent cancer development by inhibiting COX-2 and PGE2." (PMID 31440515, 2019). "This opposite splicing regulation in KIRC, may result –in part- from the opposite change in level of expression of QKI, MBNL1 and CELF2 that we detected in KIRC compared to other cancer types." (PMID 25908786, 2015). "Several RBPs such as the mRNA decapping enzyme scavenger (DCPS), CUGBP Elav-like family member 2 (CELF2), insulin-like growth factor 2 mRNA protein (IGF2BP) family, HuR, QKI-5, RBMS3, and TARBP2 play important roles in cancer biology." (PMID 35954475, 2022). "We show that many of these events are shared among different cancer types; our data also suggest that specific splicing factors, namely RBFOX2, QKI, MBNL1/2, PTBP1 and CELF2 are probably responsible for many of the alterations detected in these cancer types." (PMID 25908786, 2015). "Several important roles in cancer development have been recently found to be played by other splicing factors, such as the function of FOX2, RBM4, and CELF2 as tumour suppressors, the oncogenic effect of CELF1, or the regulation of SRSF3 splicing patterns by PTBP1 and PTBP2." (PMID 28374191, 2017). "Four genes (DAB2, DCN, CELF2 and COL1A2) have appeared previously in cancers." (PMID 22867264, 2012). "The role of CELF2 as a splicing factor in cancer has not yet been elucidated." (PMID 35941702, 2022). "In addition, negative correlation between CD44s and CELF2 mRNA was observed in pancreaic cancer tissues." (PMID 35941702, 2022). "Therefore, CELF2, similar to EZH2, was defined as a negative prognostic marker for HNSCC; however, the association of this cancer to PNI is still unknown and will need to be validated." (PMID 35571032, 2022).
neurodevelopmental disorder (1 paper, 2026). A behavioral and cognitive disorder with onset during the developmental period that involves impaired or aberrant development of intellectual, motor, or social functions. "De novo heterozygous variants in CELF2 have recently been associated with a rare neurodevelopmental disorder, yet the mechanisms linking specific variants to distinct clinical phenotypes remain poorly understood." (PMID 42275152, 2026).
neuromuscular disease (1 paper, 2016). "In fact, CELF2 has already been investigated as a therapeutic target in a neuromuscular disease called spinal and bulbar muscular atrophy, and lowering CELF2 levels can improve symptoms in a mouse model of this disorder." (PMID 27420813, 2016).